SERHL (serine hydrolase like (pseudogene))
Description:
Putative serine hydrolase.
Synonyms: SERHLP; HS126B42; BK126B4.1; dJ222E13.1
Gene: Transcribed unitary pseudogene on chromosome 22 (42,500,671 to 42,512,237, forward strand). Ensembl gene ENSG00000172250.
Diseases named in the same sentence as SERHL in open-access papers:
SERHL is named in the same sentence as 6 diseases in open-access papers, as found by Europe PMC text mining. Sharing a sentence is not in itself a finding about the gene and the disease. The quoted sentences say what the papers report.
hepatocellular carcinoma (1 paper, 2022). A malignant tumor that arises from hepatocytes. "SERHL is hypothesised to be involved in peroxisome function and was shown to be part of a lncRNA signature that predicts recurrence-free survival in hepatocellular carcinoma." (PMID 35205253, 2022).
Tetralogy of Fallot (1 paper, 2018). A congenital cardiac malformation comprising pulmonary stenosis, overriding aorta, ventricular septum defect, and right ventricular hypertrophy. "SERHL was found in tetralogy of Fallot patients and was associated with DNA methylation abnormalities." (PMID 30532766, 2018).
tumor (1 paper, 2020). "They demonstrated that MSC-AS1, POLR2J4, EIF3J-AS1, SERHL, RMST, and PVT1 were significantly upregulated in tumor samples compared to nontumor samples and were significantly associated with RFS." (PMID 33520012, 2020).
SERHL also shares sentences with these, for which no sentence is quoted: cancer (1 paper); hearing loss (1); neuroblastoma (1).